CRH (corticotropin releasing hormone)
Diseases named in the same sentence as CRH in open-access papers (continued):
Sharing a sentence is not in itself a finding about the gene and the disease.
insomnia (12 papers, 2019 to 2025). A sleep disorder characterized by difficulty in falling asleep and/or remaining asleep. "Corticotropin-releasing hormone, which regulates sleep and increases under stress, is the leading cause of insomnia, and animal experiments have shown that using corticotropin-releasing hormone inhibitors reduces the animals’ arousal times." (PMID 38550639, 2024). "Vagal neurotransmission has been demonstrated to enhance emotional regulation through GABAergic inhibition of amygdala CRH neurons, thereby establishing a link between microbial modulation and insomnia-related anxiety." (PMID 40756316, 2025). "Previous studies have shown that moxibustion can reduce serum levels of ACTH, CORT, and CRH in animal models, suggesting that it may improve insomnia by rebalancing HPA axis function." (PMID 40371071, 2025). "This led to elevated levels of inflammatory cytokines such as IL-1β and IL-6, activating the HPA axis and increasing the secretion of CRH, ACTH, and CORT, ultimately triggering insomnia." (PMID 40507808, 2025). "EA reduced brain ACh, CRH, serum ACTH, and CORT in rats with insomnia under psychological stress and then regulated the activity of the HPA." (PMID 34306138, 2021). "CRH increases the EEG frequency, leading to wakefulness or insomnia in rodents and humans." (PMID 38623339, 2024). "In sleep disorders such as insomnia, the increase in cortisol may be a marker of CRH (Corticotropin-releasing hormone) and norepinephrine activity during the night, resulting in non-restorative sleep and prolonged wakefulness." (PMID 38750102, 2024). "Several reviews have confirmed that insomnia pathophysiology involves sleep deprivation-induced sympatho-adrenal activation, driving HPA axis hyperactivity characterized by elevated cortisol, corticotropin-releasing hormone (CRH) hypersecretion, and impaired glucocorticoid receptor feedback." (PMID 40756316, 2025).
post-traumatic stress disorder (12 papers, 2012 to 2025). An anxiety disorder precipitated by an experience of intense fear or horror while exposed to a traumatic (especially life-threatening) event. "Overactivity of CRH has been implicated in the pathophysiology of the human psychiatric condition post-traumatic stress disorder (PTSD)." (PMID 35865299, 2022). "For example, CRH levels are elevated in the CSF of some post-traumatic stress disorder (PTSD) and depressed patients." (PMID 23077729, 2012). "Paeoniflorin has active impacts in decreasing the serum contents of corticosterone, corticotropin-releasing hormone, and adrenocorticotropic hormone and increasing serotonin and 5-Hydroxyindoleacetic acid in the prefrontal cortex and hippocampus in post-traumatic stress disorder mice." (PMID 39619663, 2024). "Post-traumatic stress disorder (PTSD) is a multifactorial psychological disorder that affects different neurotransmitter systems, including the central CRH system." (PMID 39595978, 2024).
stress-related disorder (12 papers, 2012 to 2024). Stress-related disorders are mental health disorders that are a result of an atypical response to both short and long-term anxiety due to physical, mental, or emotional stress. "Further evidence for a general role of CRH and CRH-BP gene polymorphisms in stress-related disorders is required." (PMID 26882083, 2016). "The individual stress response via the corticotropin-releasing hormone (CRH) system is highly likely to affect the features of many stress-related disorders." (PMID 22957021, 2012). "Because the establishment of neuronal connectivity is crucial for brain function, the action of CRH within the CNS as a modulator of synaptic plasticity and neuronal networks during development and stress-related disorders might account for long-lasting effects of stress responses." (PMID 28512295, 2017). "The BNST plays a critical role in fear acquisition/expression, which relates to stress maladaptation and the development of stress-related disorders like PTSD and involves CRH signaling." (PMID 34421556, 2021).
alcohol dependence (11 papers, 2012 to 2025). Physical and psychological dependence on alcohol. "In individuals with a higher risk to develop alcohol dependence, the reduction in the amounts of CRH and vasopressin produced following the consumption of alcohol is much higher than in control individuals." (PMID 26690116, 2015). "Previous studies in rodents with experimentally-induced alcohol dependence have demonstrated a recruitment of the corticotropin releasing hormone (CRH) system in the amygdala." (PMID 41181610, 2025). "Individuals suffering from an alcohol dependence also show a much stronger response in the Dex/CRH test when being injected CRH." (PMID 26690116, 2015). "As demonstrated in previous studies, CRH-driven hypersensitivity is crucial in the development of alcohol dependence and withdrawal, causing relapse and negative affective states." (PMID 41181610, 2025).
colitis (11 papers, 2013 to 2025). Inflammation of the colon. "We and others observe that CRH/CRF1 plays a significant peripheral role in the development of colitis and CAC in that CRF1 deficiency dramatically suppresses the colon inflammation and CAC." (PMID 38616821, 2024). "We and others have also reported the direct peripheral role of CRH/UCNs & receptors in immunity/inflammation and cancers, including colitis and colitis-associated colon cancer (CAC)." (PMID 38616821, 2024). "CRH & UCNs and the receptors are observed to be closely related to gastrointestinal system and reported to be implicated in colitis." (PMID 38616821, 2024). "Systemic CRH deficiency reduced local inflammatory responses in colonic tissues in an experimental colitis mouse model." (PMID 34873177, 2021). "Contrarily, an oncogenic role has been described for the CRHR1/CRH signaling in a colitis associated-cancer mouse model." (PMID 31614860, 2019). "We showed that mice deficient in CRH were more susceptible to DSS-induced colitis, possibly due to overproduction of IL-12 and prostaglandin E2, while having significantly decreased TLR4 levels before, but not after the colitis induction." (PMID 31614860, 2019). "Likewise, CRH is believed to be greatly related to tumorigenesis of many kinds of cancers including colon cancer via the central action during chronic stress while the peripheral effects on colitis-associated-colon cancer (CAC) are also proved." (PMID 38616821, 2024). "It is observed that trinitrobenzenesulfonic acid induces colitis with similar severity in both strains, which is inhibited by central injection of CRH." (PMID 38616821, 2024). "Paralally, abdominal symptoms evoked by CRH in colitis patients last significantly longer than in healthy controls." (PMID 38616821, 2024). "CRH induces motility of the descending colon in both healthy subjects and colitis patients, the latter with greater motility indexes." (PMID 38616821, 2024). "CRH, as a stress-response mediator, plays a significant central role in promoting the development of colitis involving colon motility, immunity and gut flora, while a few anti-colitis results of central CRH are also reported." (PMID 38616821, 2024). "Based on these reports, CRH, as the main stress mediator, is evidently a critical factor in the development of colitis." (PMID 38616821, 2024). "Up to date, little evidence has suggested a direct relationship between central CRH and the development of colitis and CAC." (PMID 38616821, 2024). "Chronic stress aggravates colitis more in Lewis than Fischer rats, which is reversed by central injection of the CRH antagonist astressin, indicating that central CRH restrains the stress’ proinflammatory action in experimental colitis." (PMID 38616821, 2024). "This review aims to mainly summarize the reports about CRH’ roles in the development of colitis and CAC, both central and peripheral, hoping to be helpful in giving a clue to future drug design of CRH relevance, as having been studied." (PMID 38616821, 2024). "They assess the role of central CRH in stress-induced worsening of colitis in inbred rat strains with hypo (Lewis) and hyper (Fischer344) CRH responses to stress." (PMID 38616821, 2024). "CRH-/- mice are observed to have more colonic inflammation than CRH+/+ mice in DDS-induced colitis model." (PMID 38616821, 2024). "While acute colonic inflammation induced CRH secretion from PVN in the hypothalamus, CRH level is found to remain at a high level in the brain after the recovery of colitis, suggesting a weak link between central CRH effect and colitis." (PMID 38616821, 2024). "Beginning with IBD models, three studies used dextran sulfate sodium (DSS) to induce colitis in male mice to investigate the effects of CRH antagonists." (PMID 35275963, 2022). "In fact, inflammatory, mesenchymal and neuronal cells derived by a peptidoglycan-induced colitis rat model, had elevated CRH expression." (PMID 31614860, 2019).
colitis (continued). "In rat and murine CD toxin A-induced ileal inflammation and TNBS-induced colitis models respectively, CRH knockdown significantly ablated inflammation, with a reduction in local IL-1β levels." (PMID 31614860, 2019). "It is therefore plausible that CRH and the CRH-R1 pathway may, at least in part, contribute to the maintenance of gut sensitization after colitis and early life stress." (PMID 40155981, 2025). "Moreover, rectal electric stimulation-induced significantly higher motility indices of the colon in colitis patients (vs healthy controls) are suppressed after administration of the selective antagonist of CRH, alphahCRH (αhCRH)." (PMID 38616821, 2024). "However, there still lack experimental evidences for a direct relationship between central CRH and colitis/CAC, while there are also relatively few investigations on CRH’s peripheral effects on CAC." (PMID 38616821, 2024). "In addition, mast cells are found to be related to CRH effects participating in the process of colitis, increasing the intestinal mucosal permeability." (PMID 38616821, 2024). "Compiling evidences show that central CRH plays indirectly a proinflammatory role in colitis." (PMID 38616821, 2024). "Besides the centrally indirect influence via mediating stress, CRH is also reported by our group and others to play a direct peripheral role in inflammation and tumors, including colitis and CAC." (PMID 38616821, 2024). "However, up to date, there still exist not many relevant experimental data on this topic, and there seems to be no absolute clearcut between the central and direct peripheral effects of CRH in colitis and colon cancer." (PMID 38616821, 2024). "observe a protective role of brain CRH from stress-induced worsening of colitis." (PMID 38616821, 2024). "Meanwhile, CRH and UCNs have been proved to play an important role in the development of colitis and CAC peripherally in which CRF1 may dominantly function as a pro-inflammatory and pro-tumorigenesis element while CRF2 may do oppositely." (PMID 38616821, 2024). "Given that CRH has a crucial role in stress and gastrointestinal system, with further evidence-reveal in the future, CRH may become a promising therapeutic target for colitis and CAC." (PMID 38616821, 2024). "Furthermore, peripheral CRH enhanced visceral nociception in recovery from experimental colitis models." (PMID 34873177, 2021). "Moreover, they demonstrate the therapeutic effect of the blockade of macrophage autophagy in DSS-induced colitis involving peripheral CRH." (PMID 34873177, 2021). "One of the reasons may be due to the different responses of DSS-induced colitis in mice species selected for the experiment, in which the main manifestation was that the concentration of CRH with anti-inflammation decrease or this model was an acute UC model." (PMID 30881446, 2019). "There are changes in the expression of CRH from the peripheral colon to the central hypothalamus, which may be an important pathway of EA or MB antidepressant response in colitis model mice, but more evidence is needed to prove this specificity." (PMID 30881446, 2019). "In support to this notion, we previously reported that CRH may protect against colitis through regulation of the toll-like receptor 4 (TLR4) expression." (PMID 31614860, 2019). "find that centrally injected CRH may have complicated influences on colitis." (PMID 38616821, 2024). "CRH, as the main stress mediator, may participate in colitis and CAC via CRF1 as a central factor." (PMID 38616821, 2024). "Secondly, peripheral CRH may play a role in colitis via influencing immune/inflammatory processes." (PMID 38616821, 2024). "Taken together, CRH, as a critical factor in stress and immunity, may participate in colitis and CAC as a centrally active molecule; meanwhile, CRH has direct peripheral effects regulating the development of colitis and CAC, both of which will be summarized in this review." (PMID 38616821, 2024).
colitis (continued). "establishes a model of psychosocial stress by peripheral administration of CRH and find that CRH aggravates DSS-induced colitis via the enhancement of intestinal macrophage autophagy." (PMID 38616821, 2024). "In the present study, we found that CRH expression in the plasma, colon, and hypothalamus of DSS-induced colitis mice was significantly reduced, which is inconsistent with the literature reports (, –8)." (PMID 30881446, 2019). "Although the mechanisms might be complicated, it is believable that the central CRH, the upper element of HPA axis and stress mediator, plays a role in CAC based on that central CRH participates in colitis (see 2.1) and the cross talks between inflammation/immunity and cancer." (PMID 38616821, 2024). "However, there exists no clearcut between CRH’s central and peripheral effects in colitis and CAC because of cross-talks between HPA axis and the immune system, and also between central and myenteric neurons." (PMID 38616821, 2024). "WAS, but not colitis, also altered the activity of the hypothalamic CRH system." (PMID 26066467, 2015).
melanoma (11 papers, 2007 to 2025). A malignant, usually aggressive tumor composed of atypical, neoplastic melanocytes. "Also, the observation of a differential association between CRH and overall survival in male patients may reflect systemic neuroendocrine alterations induced by advanced melanoma." (PMID 40917468, 2025). "In this study, we demonstrated that primary melanomas exhibit significantly higher expression of CRH compared to benign melanocytic nevi." (PMID 40917468, 2025). "The intensity of CRH expression in melanoma metastases was stratified by sex and correlated with patient survival." (PMID 40917468, 2025). "The aim of this study was to analyze CRH expression in nevi and compare it to primary melanoma and melanoma metastasis." (PMID 40917468, 2025). "It is known that CRH induces a dose-dependent increase in intracellular calcium levels in melanoma cell lines and in the epidermoid carcinoma cell line A431." (PMID 40917468, 2025). "This is different from the pattern observed in melanoma, where benign nevi exhibit lower CRH expression than primary melanomas." (PMID 40917468, 2025). "Compared to melanoma, BCCs and SCCs showed weaker CRH expression, which was in line with the finding that in vitro, CRH stimulation of the A431 cells reduced their proliferative activity." (PMID 40917468, 2025). "Immunohistochemical analysis of cutaneous tumors has shown that 80% of melanomas, 70% of squamous cell carcinomas, and 10% of basal cell carcinomas are highly immunoreactive for CRH." (PMID 34068618, 2021). "It has been suggested that in human melanoma cells, CRH and urocortin regulate TYRP1 gene expression via NURR1/NUR77 production." (PMID 34884858, 2021). "Another important possible effect of CRH is the reduction of tumor growth rate and was demonstrated in vivo on B16 melanoma cell lines." (PMID 34068618, 2021). "Additionally, we observed that increased CRH expression is more pronounced in melanoma metastases from women than from men." (PMID 40917468, 2025). "In melanoma, CRH expression in metastases may be an important prognostic factor for overall survival in men, which needs further evaluation." (PMID 40917468, 2025). "The expression of CRH in melanoma metastases was further correlated with patient survival." (PMID 40917468, 2025). "Higher CRH expression was also found in melanoma metastases from women compared to men." (PMID 40917468, 2025). "This could potentially explain the increased CRH expression observed in melanoma metastases of females." (PMID 40917468, 2025). "Quantification revealed a significantly higher expression of CRH in primary melanomas than in nevi." (PMID 40917468, 2025). "Interestingly, higher CRH expression in melanoma metastases correlated with worse overall survival only in men." (PMID 40917468, 2025). "They found strong CRH expression in melanoma and SCC, and intermediate in BCC." (PMID 40917468, 2025). "CRH stimulates melanoma cells invasion via ERK1/2 signalling pathway." (PMID 35334544, 2022). "Furthermore, in melanoma cell culture CRH induced the expression of POMC mRNA, while a CRH antagonist suppressed it." (PMID 34068618, 2021). "Additionally, CRH together with CRH-R, are expressed in melanoma cell lines as well as in primary and metastatic melanoma." (PMID 34068618, 2021). "CRH seems to be a significant mediator involved in the migration of melanoma cells." (PMID 34068618, 2021). "Thus we investigated if, in mice bearing B16-F10 melanoma metastases, increased circulating IL-6 did affect CRH production." (PMID 23517603, 2013). "Additionally, the increased locoregional immunosuppressive and proangiogenic effects of CRH might contribute to the development of a more aggressive melanoma subtype." (PMID 40917468, 2025). "The receptor for CRH, CRHR1, is expressed by keratinocytes and melanocytes, as well as their malignant counterparts, squamous carcinoma and melanoma cells." (PMID 40917468, 2025).
melanoma (continued). "Three TMAs with samples from 49 primary melanomas, 45 metastatic melanomas, and 40 melanocytic (nondysplastic) nevi from melanoma patients were stained for CRH expression." (PMID 40917468, 2025). "Melanoma metastases also showed higher CRH expression than nevi, although the difference was not significant." (PMID 40917468, 2025). "Meanwhile, the human melanoma line, which is shown to express CYP17, CYP21A2, POMC and CRH genes, could metabolize progesterone to corticosterone." (PMID 33529200, 2021). "In addition, while we analyzed nearly 94 melanomas/melanoma metastases, we only quantified CRH expression of small tumor sections rather than the entire tumor." (PMID 40917468, 2025). "The higher CRH expression in melanoma metastases from females has not been described yet." (PMID 40917468, 2025). "Moreover, the coordinated activity of the CRH-POMC axis was demonstrated in both primary and metastatic melanoma, colocalization of CRH and POMC peptides being emphasized in the great majority of CRH positive melanomas." (PMID 34068618, 2021). "Therefore, a potential explanation for the increased mortality rate among men with increased CRH expression in melanoma metastasis could be attributed to the absence of protective estrogen effects." (PMID 40917468, 2025). "Since CRH has been described in several types of skin cancer, it is of interest to determine whether high CRH expression correlates with decreased or increased malignancy in human nonmelanoma and melanoma skin cancers." (PMID 40917468, 2025).